TLR3 (toll like receptor 3)
Diseases named in the same sentence as TLR3 in open-access papers (continued):
Sharing a sentence is not in itself a finding about the gene and the disease.
infection (continued). "While TLR3 ablation protected mice from WNV lethal infection by decreased systemic TNF-α and IL-6 production and BBB permeability, there is a report demonstrating that TLR3 molecules are essential in protecting from WNV infection." (PMID 25188232, 2014). "At day 2 post-infection, the virus provoked a significant increase on the levels of transcription of IL-6, CK10 and TLR3." (PMID 25333488, 2014). "We did not detect any statistically significant increase in expression of TLR3, TLR7, and TLR8 transcripts post-infection, however some trends potentially indicating a viral induction were observed (data not shown)." (PMID 24712747, 2014). "Both TLR3 and RIG-I can sense HCV RNA (although they recognize different viral ligand forms) early after infection and initiate signaling pathways culminating in the induction of an IFN response that curtails HCV replication." (PMID 25111807, 2014). "The knock down of TLR3 mRNA significantly impaired poly I:C-stimulated resistance to EIAV, greatly reducing the expression of sELR1 and IFNβ and lowered the level of infection resistance induced by EIAVFDDV13." (PMID 25106750, 2014). "West Nile virus (WNV) vaccination studies revealed that MyD88 and TLR3 are both required for efficient humoral immune responses, and during a WNV infection Rig-I and MDA5, as well as TLR3 and TLR7 are involved in immune recognition." (PMID 25539593, 2014). "Importantly, LRV2-Lae mirrored our previous findings with LRV1-Lg, and further supported the hypothesis that LRV dsRNA was a major innate immunogen as measured by the TLR3-dependent production of two key pro-inflammatory cytokines following infection of macrophages in vitro." (PMID 24762979, 2014). "The protein levels of TLR3, RIG-I, and MDA-5 were all elevated with the extension of the infection duration." (PMID 24701034, 2014). "Therefore, since TLR3 and TLR4 molecules contribute to the generation of a normal IFN response through activation of IRF-3, IRF-5, and IRF-7 after infection with neurotrophic virus, we tested whether the ablation of TLR3 and TLR4 molecules affected type I innate responses in JEV infection." (PMID 25188232, 2014). "At the early phase of infection, analysis of the spleen provides an insight into how TLR3 and TLR4 molecules modulate innate immune and inflammatory responses immediately after infection, because JEV was administered intraperitoneally." (PMID 25188232, 2014). "Infection of cells with the flavivirus, dengue virus (DENV) is recognised by the toll-like receptor-3 (TLR3), retinoic acid inducible gene–I (RIG-I) and melanoma differentiation associated gene-5 (MDA5) pathways to induce the IFN response." (PMID 23638199, 2013). "Consistent with previous reports, B. thailandensis upregulated expression of TLR1 and TLR2 by two h post-infection, and increases in TLR1, TLR2, TLR3, TLR4, and TLR5 mRNA expression were observed by eight h post-infection." (PMID 23675544, 2013). "TLR3 and IFN-b mRNA expression increased significantly following infection with E16 and E30 (P<0.033 and P<0.039 respectively) compared to E4-inoculated islets and the uninfected control." (PMID 24223733, 2013). "The expression of MdTLR3 is significantly upregulated in the brain reaching a maximum at 48 h post infection (pi) with HPAIV H5N1, which is similar to chicken TLR3." (PMID 24016341, 2013). "It has previously been reported that TLR3 is required for the generation of CD8 T cell immunity to HSV-1 after flank infection and our results indicate that TLR3−/− mice have reduced virus-specific CD8 T cell responses after systemic and footpad infections." (PMID 24204273, 2013). "The results from the real-time quantitative PCR measurements indicated that the levels of TLR3-4 and TLT7-8 increased in a time-dependent manner after RSV infection, and these levels continued to increase up to 24 h after infection." (PMID 24039959, 2013).
infection (continued). "In lung epithelial cells, both TLR3 and RIG-I play a critical role in IAV pathology, and against this infection." (PMID 23592984, 2013). "TLR3 and IFN-beta mRNA expression increased significantly following infection with E16 and E30 (P<0.033 and P<0.039 respectively)." (PMID 24223733, 2013). "After infection with RSV or treatment with PolyI:C, the expression of intracellular TLR3 significantly increased." (PMID 24039959, 2013). "The levels of TLR3 and TLR7-8 peaked at 5 days after infection, while the levels of TLR4 peaked at 9 days after infection." (PMID 24039959, 2013). "The TLR3 levels peaked at 9 h after hMPV infection, and the levels of TLR4 and TLR7-9 peaked at 12 h after infection, then started to decline." (PMID 24039959, 2013). "It was shown that at the incipient stage of infection, after exposure of viral particles to the acidic endosomal pH, DENV RNA interacts with TLR3 molecules present in intracellular compartments and triggers IL-8 and IFN-α/β secretion." (PMID 22970315, 2012). "TLR3 and several of the genes involved in the TLR signaling pathway were significantly upregulated during infection." (PMID 22363523, 2012). "The TRIF-dependent pathway is indispensable for the induction of type 1 IFNs through TLR3 and TLR4, but the role of type 1 IFNs in the resistance to infection with T. cruzi is controversial." (PMID 22496959, 2012). "Of note, human neutrophils express all TLRs, except TLR3, respond to TLR agonists, including TLR9, and TLR stimulated neutrophils recruit innate immune cells to sites of infection." (PMID 23028824, 2012). "HRV is endocytosed by epithelial cells, and is therefore primarily detected by TLR3 in the endosome early in the infection process and by RIG-I and MDA-5 later in infection following upregulation of these PRRs." (PMID 22974166, 2012). "Expressions of TLR3, IFNα, IL6, IL8 and CCL5 in the lungs following infection with the two HPAIVs were low." (PMID 21826229, 2011). "The mRNA levels of both TLR3, and RIG I showed changes at 18 hr post-infection and densitometry analysis was performed on these data." (PMID 22206025, 2011). "We observed that the expression levels of TLR3 and RIG-I were down regulated after infection in LH86 cells." (PMID 21695051, 2011). "In particular, the induction of strong type I IFN production, following infection with TMEV, is mediated by TLR3 and MDA5-mediated signals." (PMID 22189096, 2011). "Because CVB3 did not elicit a pronounced translocation of IRF3 into the nucleus during infection of HEK293 cells, we investigated the role of several PRRs in mediating CVB3 recognition–TLR3, RIG-I, and MDA5." (PMID 21436888, 2011). "The mRNA expressions of TLR3, TGFβ3 and SMAD7 in the lungs following infection with Pigeon04 were negatively correlated with viral replication." (PMID 21826229, 2011). "It has been previously reported that following infection of human postmitotic neurons with RABV, there is an increased production of IFN-ß and TLR-3 mRNAs." (PMID 20661430, 2010). "We found that the 3d mice are highly susceptible to infection with T. gondii, suggesting the possibility that the combined action of TLR3, TLR7 and TLR9 is critical for host resistance to infection with T. gondii." (PMID 20865117, 2010). "For HSV, TLR2, TLR3, TLR9, the MAVS pathways and the RNA polymerase III pathway have been identified as sensing the infection and inducing the production of IFN-α/β and cytokines." (PMID 21994567, 2009). "Instead, TLR3 signaling on macrophages is required to establish protection and ensure survival following CB4 infection." (PMID 19122812, 2009). "For example, compared with infection with low pathogenicity influenza virus (IAV) strains, lethal IAV strain infection preferentially upregulated TLR3 to a greater extent, which induced dysregulation of cytokines such as IL-6 and TNF-α and enhanced viral replication." (PMID 41221396, 2025).
infection (continued). "When the expression of TLR3/RLR was inhibited in bat organoids, they allowed the infection and replication of SARS‐CoV‐2, suggesting that TLR3 and RLR may be conserved pathways mediating antiviral responses in bat and human intestinal organoids." (PMID 39973397, 2025). "Indeed, the expression levels of specific genes involved in the cellular response to WCBV infection were similar to what observed following the infection with RABV (e.g., Ddx58, Inf1β, Tlr3-4, and Nfkb)." (PMID 39846740, 2025). "A transcriptomic analysis of the host response to mpox infection in multiple cells revealed repression of TLR3 target genes in MPXV-infected cells, and transcripts from the predicted dsRNA binding protein were also detected during infection in these cell types, supporting our findings." (PMID 40498594, 2025). "After that, the completed construct was docked against TLR3 and TLR2 by using Cluspro 2.0 tool to examine sufficient binding to elicit an immunological response, TLR3 activates antiviral defenses during infection and aids in the detection of infectious dead cells." (PMID 39854342, 2025). "For instance, in an Aspergillus fumigatus infection model, TLR3, TRIF, and IFN-β mRNA expression in infected mouse lung tissue was significantly increased, reaching its peak at 24 hours, thereby confirming effective pathway activation during infection.." (PMID 41459537, 2025). "In in vitro megakaryocytic models (MEG-01), DENV infection has been reported to induce elevated levels of RIG-I, MDA5, and TLR3 within 48–72 h, accompanied by increased IFN-β expression as early as the first day post-infection —in contrast to the delayed response observed in K562 cells." (PMID 41303574, 2025). "For example, mice lacking TLR3 showed greater resistance to infection with several viruses, such as Punta Toro, vaccine virus VACV, and influenza virus, which is assumed to be due to TLR-3-mediated overproduction of inflammatory mediators." (PMID 40909801, 2025). "For example, mice lacking TLR3 showed greater resistance to infection with several viruses, such as Punta Toro, vaccine virus, and influenza virus, which is assumed to be due to TLR-3-mediated overproduction of inflammatory mediators." (PMID 41254402, 2025). "The AG234 infection primarily activated the immune response at 48 hpi, characterised by a significant mRNA up-regulation of TLR3, TLR21, IL-1β and INF-γ compared to the negative control." (PMID 40426284, 2025). "The present study investigated the association of polymorphisms in the TLR3 gene (rs5743305 T/A and rs3775291 C/T) with HTLV-1 infection and infection status (related to the presence or absence of symptoms of inflammatory disease)." (PMID 40831704, 2025). "PRRs like the toll-like receptor 3 (TLR3) of some innate systems could recognize dsRNA which was a common viral replication intermediate and a strong indicator of infection." (PMID 38322849, 2024). "Our qPCR analysis reveals significantly elevated RIG-I and TLR3 expression in LNCaP cells compared to PANC-1 upon rSFV-infection even in the absence of transgenic-CXCL10 expression." (PMID 38425844, 2024). "A single amino acid change from serine (S) to arginine (R) at position 339 within the CTLD of human CLEC18A has been shown to increase the binding affinity of toll-like receptor 3 (TLR3) and CLEC18A to poly(I:C), enhancing interferon (IFN) production against infection." (PMID 38764023, 2024). "At the earlier time points post-infection, we did not observe any overlap with down-regulated mRNAs; however, 27 up-regulated mRNAs were common to all early treatment groups, including TLR3, IFIT5, IFIH1 (MDA5), MX1, RSAD2 (viperin), CMPK2, SOCS1, and SCNN1D." (PMID 38675946, 2024). "Second, TLR3 recognizes the viral dsRNA intermediates generated during HSV-1 replication, and the activation of TLR3 induces receptor-interacting kinase-3 (RIPK3)-dependent necrosis to reduce viral propagation, which is crucial for immune defence against infection." (PMID 38185640, 2024).
infection (continued). "Hepatic myeloid and lymphoid cells could express TLR3, and the percentages of TLR3-expressing MDSC, macrophages and neutrophils were increased after infection." (PMID 38172683, 2024). "Prophylactic treatment with the TLR3 agonist Poly (I:C), significantly increased the mean day of death in hamsters, while treatment with Poly (I:C) administered after infection (therapeutically) did not protect hamsters from mortality." (PMID 39459957, 2024). "Additionally, in the context of other arboviruses, Tlr3 has been shown to be both protective and pathologic during West Nile virus (WNV) infections in the brain and is expressed in response to infection in both wild-type and Ifnar1−/− mice." (PMID 37800949, 2023). "Several TLRs, TLR3 and TLR9 can recognize viral nucleic acids or viral protein produced by PRRSV leading to release many cytokines, such as IL-6, TNF-α and IFN-γ at the early stage of infection." (PMID 37099541, 2023). "This includes HCV, HBV, and endogenous dsRNA from apoptosis cells which activate TLR3 signaling in the absence of infection." (PMID 36654880, 2023). "TLR3 reached peak levels of mRNA expression at 48 hpi following infection by each virus, and the mRNA levels were not statistically different to each other." (PMID 37766212, 2023). "TLR3 also recognizes endogenous dsRNA from apoptosis cells and activates signaling cascades in the absence of infection." (PMID 36654880, 2023). "In line with general MLN hypertrophy in response to RV infection, overall cellularity and CD8 T cell numbers were increased upon infection, and this was not affected by the absence of TLR3-signaling." (PMID 35464475, 2022). "The MyD88-activating agonist CpG (TLR9 agonist), but not TRIF-activating Poly I:C (TLR3 agonist), protects against infection in a macrophage-dependent manner." (PMID 36439136, 2022). "Nonetheless, TLR3/RLR inhibitor CYT387 indeed enhanced bat organoid infection of SARS-CoV-2 and CoV-HKU4 more prominently than the human counterparts at the early phase of infections." (PMID 36529763, 2022). "Six-to-ten week old TLR3 depleted mice are more resistant to lethal intraperitoneal WNV infection as there is less viral RNA and inflammation present in the brains of mice starting at 3 days post-infection, suggesting that WNV modulates TLR3 for pro-viral purposes." (PMID 35409387, 2022). "Previous studies have demonstrated that either single-PDCoV or -PEDV S-INDEL, but not non-S-INDEL, infection significantly upregulated TLR3 by 3 DPI12,17." (PMID 36376395, 2022). "For example, heat-iMVA infection triggered higher levels of IFN-inducible genes than MVA, including Ifih1 (MDA5), Ddx58 (RIG-1), Oasl2, Oas3, TLR3, Nod1, Ifna4, Ifnb1, Ccl5, Cxcl9, Cxcl10, and members of the guanylate binding protein (Gbp) family, as largely dependent on STING (marked as b)." (PMID 36261460, 2022). "MCs release interferons (IFNs) following Toll-like receptor 3 (TLR3) activation, influenza A and respiratory syncytial virus (RSV) infection and release chemokines and cytokines which recruit immune cells following infection with dengue virus or RSV." (PMID 36366528, 2022). "Our objective was to investigate the role of innate immune antiviral signaling triggered by TLR3, macrophage activation and cytokine expression in the intestinal lamina propria (ILP) at the early stage of infection on the pathogenicity of IBDV strains with different virulence." (PMID 35215986, 2022). "TLR3 and RIG-I/MDA-5 are prominent targets for such downregulation, as these molecules act synergistically to produce the antiviral state against DENV1, so as to restrict the infection." (PMID 35632732, 2022). "Regarding the activation of natural killer (NK) cells during infection, we demonstrated that mild patients who were naturally infected by DENV had increased frequencies of CD107a (a degranulation marker), TLR3 and tumor necrosis factor- (TNF-) related apoptosis inducing (TRAIL)." (PMID 35632732, 2022).
infection (continued). "However, we did note a trend (p < 0.1) for interactions between infection and LB supplementation for the expression, of ARG1, TLR3, IL1B, and CTLA4, with the infection-induced expression of these genes being attenuated to some extent by LB." (PMID 35069576, 2021). "TLR3 and RIG-I mRNA expression levels in H3N2 CIV-infected cells were significantly higher (8.4- and 6.4-fold, respectively; p < 0.001) than those in mock-infected cells at 12 h post-infection." (PMID 34099596, 2021). "Previously, we showed an increased expression of TLR2, TLR3, TLR5, and TLR8 in pulmonary epithelial cells at 48 h post-infection by genetically diverse M. tuberculosis clinical strains of East-Asian and Euro-American lineages, leading to production of a diverse range of inflammatory cytokines." (PMID 34502407, 2021). "TLR3+/- mice have three times the amount of IFN-β than IFN-α in the sera at baseline, prior to CB4 infection, compared to wt mice and by day 3 post infection, TLR3+/- mice dramatically lose IFN-β production versus IFN-α in the sera (ratio of 0.14) compared to wt mice (ratio 0.71)." (PMID 34804036, 2021). "Whether regulation of TLR3 by VitD3 is dose-dependent, or if different baseline levels of VitD3 in DENV- infected patients are important for host response and control of infection remains to be studied." (PMID 34634046, 2021). "In line with the reduced production of IFN-λ in cells expressing TLR3, we observed significantly increased ZIKV replication in these cells 48 h after infection, i.e., at a time point when enhanced viral replication also became detectable in hNPCs and human astrocytes (respectively)." (PMID 33658344, 2021). "Meanwhile, the addition of the TLR3 inhibitor reduced the secretion of IFN-α and IFN-β 24 h post-infection, while the addition of the TLR7 inhibitor reduced the expression of these type I IFNs 48 h post-infection (p < 0.001; Student’s t-test)." (PMID 34576716, 2021). "In particular, TLR3 might act via IRF3, producing interleukin (IL)-1α, IL-1β, IL-4, IL-6, and IFN-α and IFN-β, during the first 24 h post-infection." (PMID 34576716, 2021). "The observed difference could be explained by the time post-infection at which the analysis was carried out, suggesting that CHIKV activates TLR3 more rapidly than MAYV." (PMID 33799906, 2021). "Adjuvant β-defensins, a TLR3 agonist, acts as a strong immunostimulant that provokes an immune response by binding to its corresponding receptors, TLRs and CCR6, activating both immature dendritic cells and naïve T-cells at the infection location." (PMID 34452050, 2021). "This suggests that changes in TLR3 expression support the systemic production of IFN-α rather than IFN-β after CB4 infection, contrary to what we have previously observed for MDA5+/- mice, where IFN-β responses are more significantly favored." (PMID 34804036, 2021). "Moreover, upon in vitro infection of BV2 cells with DENV, pharmacological inhibition of TLR3 signaling abrogated microglia migration in wound healing assays." (PMID 34696494, 2021). "In particular, TLR3 might act via IRF3-producing IFN-α and IFN-β during the first 24 h post-infection." (PMID 34576716, 2021). "With our MDA5+/- and TLR3+/- CB4-infection models, we have identified, using a virus clinically linked to T1D, how changes in MDA5 and not TLR3 signaling are critical in producing an IFN-I response and subsequent adaptive responses that protect from T1D." (PMID 34804036, 2021). "PrimePCR array analysis of hNS/PCs showed that the mRNA levels of inflammatory cytokine related genes (IL-1A, TNFα, IL28A, IL29, NF-KB2), chemokines (CSF2, CCL3, CCL4, CXCR3),TLRs (TLR3, TLR8), IL-10, and Casp9 were all reduced in the Smaducin-6 treated group following ZIKV-FSS13025 infection." (PMID 32544190, 2020). "Although these responses were dependent on TLR3, the polyI:C-treated mice were not able to completely control infection, so additional mechanisms must be necessary to clear virus." (PMID 32751803, 2020).